EMX2 (empty spiracles homeobox 2)
Description:
Transcription factor, which in cooperation with EMX1, acts to generate the boundary between the roof and archipallium in the developing brain. May function in combination with OTX1/2 to specify cell fates in the developing central nervous system. In the inner ear, it controls the distribution of GPR156 at hair cell boundaries, and regulates the organization of stereociliary bundles in opposite orientations across the line of polarity reversal (LPR).
Tractability: No criterion of Open Targets' tractability assessment is met for any kind of drug.
Gene: Protein-coding gene on chromosome 10 (117,542,445 to 117,549,546, forward strand). Ensembl gene ENSG00000170370.
Subcellular location: Nucleus; Cell projection, axon
Subcellular location (Human Protein Atlas): Nucleoplasm
Pathways (Reactome):
Developmental Biology: Formation of the nephric duct
Gene Ontology:
Molecular function: protein binding; sequence-specific double-stranded DNA binding; DNA-binding transcription factor activity, RNA polymerase II-specific; RNA polymerase II cis-regulatory region sequence-specific DNA binding; DNA binding
Biological process: brain development; central nervous system development; neuron differentiation; regulation of transcription by RNA polymerase II; stereocilium bundle organization; regulation of DNA-templated transcription
Cellular component: chromatin; nucleus; axon
Genetic constraint (gnomAD): Loss-of-function variants: 6 observed, 23.73 expected, observed/expected ratio (o/e) 0.25, 90% interval 0.14 to 0.5. The upper end of that interval is the gene's LOEUF score, 0.5, which puts it in group 2 of 6, group 1 being the genes least tolerant of losing a copy. Missense variants: 302 observed, 349.86 expected, observed/expected ratio (o/e) 0.86, 90% interval 0.79 to 0.95. Synonymous variants: 175 observed, 160.85 expected, observed/expected ratio (o/e) 1.09, 90% interval 0.96 to 1.23.
Gene-disease validity (ClinGen):
ClinGen rates the evidence that EMX2 causes each of these diseases.
schizencephaly (autosomal dominant): Limited.
Homologues: Orthologues: chimpanzee EMX2 (100% identical), dog EMX2 (100% identical), macaque EMX2 (100% identical), mouse Emx2 (100% identical), pig EMX2 (100% identical), rabbit EMX2 (100% identical), rat Emx2 (100% identical), guinea pig EMX2 (99% identical), tropical clawed frog emx2 (93% identical), zebrafish emx2 (93% identical). Paralogues in human: EMX1 (66% identical), VAX2 (22% identical), VAX1 (21% identical).
Diseases named in the same sentence as EMX2 in open-access papers:
EMX2 is named in the same sentence as 69 diseases in open-access papers, as found by Europe PMC text mining. Sharing a sentence is not in itself a finding about the gene and the disease. The quoted sentences say what the papers report.
lung carcinoma (11 papers, 2011 to 2025). "For example, EMX2 downregulation has been associated with poor prognosis in glioblastoma, ovarian cancer, and lung cancer." (PMID 40564092, 2025). "Downregulation of the EMX2 gene has been linked to the development of several solid tumors, such as gastric cancer, lung cancer, endometrial cancer and colorectal cancer, while restoration of EMX2 suppresses cancer progression." (PMID 38007497, 2023). "For example, EMX2 has been demonstrated as a tumor suppressor in lung cancer, and low EMX2 expression is associated with decreased overall survival and recurrence free survival in patients with lung adenocarcinomas." (PMID 23029345, 2012). "In the past decade, there are emerging evidence showed that EMX2 also acts as a tumor suppressor gene in multiple cancers, such as lung cancer, gastric cancer and glioma." (PMID 30576338, 2018). "In lung cancer, EMX2 is dramatically downregulated due to its promoter methylation, which enhances cell proliferation, invasive phenotypes and canonical WNT signaling." (PMID 30576338, 2018). "In this study, lung cancer SCC patients with positive EMX2 staining significantly benefited from adjuvant chemotherapy in two independent cohorts." (PMID 26132438, 2015). "Since most patients with lung cancer receive chemotherapy, we sought to determine if EMX2 expression is predictive of response to chemotherapy in vitro." (PMID 26132438, 2015). "We have previously shown that EMX2 suppresses lung cancer cell proliferation and sensitizes lung adenocarcinoma cells to cisplatin in vitro." (PMID 26132438, 2015). "EMX1 and EMX2 are homeodomain-containing transcription factors, and the function of EMX2 has been linked to the WNT signaling pathway, which has an important role as a suppressor in lung cancer." (PMID 31467637, 2019). "Several lines of evidence suggest that EMX2 is down-regulated in lung cancer." (PMID 28830374, 2017). "Epigenetic silencing of the EMX2 expression may be important for aberrant activation of the Wnt signaling in lung cancer, and consequent proliferation and metastasis." (PMID 23029345, 2012). "Another gene Empty Spiracles, Drosophila, 2, HOMOLOG OF; (EMX2) has also been shown to be dramatically downregulated in lung cancer tissue samples by methylation of its promoter, and restoration of EMX2 gene expression sensitized lung cancer cells to cisplatin." (PMID 24212667, 2011). "Downregulation of EMX1/EMX2 genes has been documented to be correlated with the development of several epithelial‐originated solid tumors, such as gastric cancer, lung cancer, endometrial cancer, and colorectal cancer, and restoration of these genes suppressed cancer progression." (PMID 35849030, 2022). "Moreover, EMX2 has been shown to be a predictive marker for survival in lung cancer." (PMID 28830374, 2017).
schizencephaly (10 papers, 2009 to 2024). "Despite reports of EMX2 as a ‘schizencephaly gene’, evidence of a role for EMX2 mutations in schizencephaly is lacking." (PMID 32895508, 2020). "The causes of schizencephaly are heterogeneous and can include teratogens, prenatal infection, maternal trauma, or EMX2 mutations." (PMID 25690450, 2015). "Nevertheless, the majority of authors currently believe that there is insufficient evidence that would confirm the validity of the theory, since the EMX2 gene mutation is noted only in some children with schizencephaly." (PMID 25690450, 2015). "Point mutations in human EMX2 result in severe schizencephaly." (PMID 39628661, 2024). "The etiopathogenesis of schizencephaly remains unclear, but it may result from external factors like middle cerebral artery stroke or genetic factors like EMX2 gene mutation." (PMID 37323273, 2023). "Mutations in EMX2 have been noted in patients with severe schizencephaly." (PMID 36070311, 2022). "Emx2 has also been associated with the diseases of schizencephaly." (PMID 31671093, 2019). "Moreover, heterozygous mutations of EMX2 in humans have been implicated in some cases of a rare developmental disorder, schizencephaly, characterized by different clinical features, including mental retardation, hypotonia, epilepsy and spasticity." (PMID 21214944, 2011). "In humans, heterozygous EMX2 mutations have been associated with Schizencephaly [OMIM #269160], but no MAC or other ocular malformations have previously been reported associated with mutations in this gene." (PMID 36830662, 2023). "Two cases in our pediatric cohort did have relevant histories: one child had a known mutation of the EMX2 gene and the other had a strong family history of schizencephaly but no known genetic abnormality at the time of the MR study." (PMID 30027296, 2018). "Early reports linking schizencephaly to mutations in the EMX2 gene have not been borne out." (PMID 30027296, 2018).
gastric cancer (7 papers, 2012 to 2023). A primary or metastatic malignant neoplasm involving the stomach. "EMX2 down-regulation was associated with promoter hypermethylation and the adenoviral delivery of EMX2 in a mouse model of gastric cancer significantly suppressed tumor growth." (PMID 28830374, 2017). "More recently, loss of EMX2 expression has been demonstrated in gastric cancer cell lines and primary gastric cancer." (PMID 28830374, 2017). "This is supported by observations in lung and gastric cancers, where EMX2 and the Wnt pathway are also related." (PMID 34364391, 2021). "In gastric cancer, adenovirus-mediated EMX2 overexpression significantly inhibits cell proliferation and the Wnt signaling pathway both in vitro and in a gastric cancer xenograft model in vivo and prolongs the survival of tumor-bearing mice." (PMID 30576338, 2018). "Accordingly, recent studies suggest a possible involvement of EMX2 in several human cancers including lung, endometrial and gastric cancer." (PMID 28830374, 2017). "In this study, we reported that down-regulation of EMX2 expression was significantly correlated with EMX2 promoter hypermethylation in gastric cancer." (PMID 23029345, 2012). "Taken together, our results demonstrate a therapeutic potential of adenovirus-delivered EMX2 to treat gastric cancer." (PMID 23029345, 2012). "We also show that restoration of EMX2 using an adenoviral delivery system inhibits cell proliferation and Wnt signaling in vitro, and results in better survival of a gastric cancer xenograft model in vivo." (PMID 23029345, 2012). "Taken together, these results support an important role of EMX2 in suppression of Wnt pathway in gastric cancer." (PMID 23029345, 2012). "We examined EMX2 expression in nine human gastric cancer cell lines, as well as tumor and paired adjacent normal tissues from ten gastric cancer patients." (PMID 23029345, 2012). "The function of EMX2 has been linked to Wnt signaling pathway; therefore we studied the relationship between EMX2 and Wnt signaling in gastric cancer." (PMID 23029345, 2012). "We established the MKN28 and AGS xenograft models to explore the therapeutic potential of adenovirus-delivered EMX2 for gastric cancer in vivo." (PMID 23029345, 2012). "We demonstrate the EMX2 downregulation and its correlation with methylation status of the gene promoter region in gastric cancer." (PMID 23029345, 2012). "In this study, we provide insights on these questions by investigating EMX2 in human gastric cancer." (PMID 23029345, 2012). "Our data strongly suggest the therapeutic potential of using the Ad-EMX2 as gene therapy for future treatment of patients with gastric cancer." (PMID 23029345, 2012). "A larger number of patient samples need to be examined to further validate the finding of methylation-silencing of EMX2 in gastric cancer." (PMID 23029345, 2012). "We examined methylation status of the EMX2 promoter in nine gastric cancer cell lines and normal gastric tissue." (PMID 23029345, 2012). "Taken together, our results strongly suggest the down-regulation of EMX2 expression was significantly correlated with the EMX2 promoter hypermethylation in human gastric cancer." (PMID 23029345, 2012). "Nevertheless, our results provide a first direct evidence to support this mechanism in gastric cancer and identify EMX2 as a putative novel tumor suppressor in gastric cancer." (PMID 23029345, 2012). "Our study suggests that EMX2 is a putative tumor suppressor in human gastric cancer." (PMID 23029345, 2012). "Our results demonstrate the anti-proliferation function of EMX2 in gastric cancer cells." (PMID 23029345, 2012). "In this study, we report EMX2 as a putative tumor suppressor in human gastric cancer." (PMID 23029345, 2012). "We next examined the role of EMX2 on cell growth of gastric cancer cells." (PMID 23029345, 2012).
gastric cancer (continued). "Nevertheless, our in vivo study of Ad-EMX2 infection suggests that EMX2 gene therapy may have potential to become a clinical anti-tumor therapeutic strategy for the treatment of gastric cancer in the future." (PMID 23029345, 2012). "Finally, our results indicate the potential of using EMX2 gene therapy for the treatment of gastric cancer." (PMID 23029345, 2012). "To establish the possible role of EMX2 in pathological progression of human gastric cancer, we analyzed EMX2 expression using total RNA that we obtained from fifteen gastric dysplasia samples and twenty gastric cancer surgical samples." (PMID 23029345, 2012). "Moreover, our observation of EMX2 dowregulation in non-invasive gastric dysplasia supports a possible important role of EMX2 in pathological progression of human gastric cancer." (PMID 23029345, 2012). "The adenoviral-EMX2 may have potential as a novel gene therapy for the treatment of patients with gastric cancer." (PMID 23029345, 2012). "In addition, we investigated important oncogenic pathways through which EMX2 functioned in gastric cancer, and found that Wnt signaling pathway may play a key role mediating the EMX2 function." (PMID 23029345, 2012). "Restoring EMX2 expression using an adenovirus delivery system in gastric cancer cell lines lacking endogenous EMX2 expression led to inhibition of cell proliferation and Wnt signaling pathway both in vitro and in a gastric cancer xenograft model in vivo." (PMID 23029345, 2012). "The opposite effects were also produced when the EMX1/EMX2 genes were silenced, indicating that the Wnt pathway is inactivated in the presence of EMX gene expression, as has been preliminarily demonstrated for EMX2 in other tumors, such as lung and gastric cancer." (PMID 34364391, 2021).
glioblastoma (6 papers, 2016 to 2025). The most malignant astrocytic tumor (WHO grade IV). "Within this signature, the EMX2 gene encodes a homeodomain transcription factor that we found was down regulated in glioblastoma." (PMID 30514244, 2018). "Maintenance of tumorigenic potential by glioblastoma cells requires EMX2 repression, since forced EMX2 expression prevents tumour formation." (PMID 31468686, 2019). "Restoration of EMX2 expression in U87 glioblastoma cells significantly inhibited cell proliferation." (PMID 30514244, 2018). "A major and original finding from this study is that EMX2’s anti-proliferative effect is significantly reversible after 8 days of induction in U87 and U251 glioblastoma cell lines." (PMID 30514244, 2018). "We found that Emx2 overexpression induced the collapse of seven out of seven in vitro tested glioblastoma cell lines." (PMID 27191499, 2016). "All that points to Emx2 as a novel, promising tool for therapy of glioblastoma and prevention of its recurrencies." (PMID 27191499, 2016). "Next, in the majority of glioblastoma cultures analyzed in the present study, endogenous EMX2-mRNA was undetectable." (PMID 27191499, 2016). "We can hypothesize that EMX2 may control the transition (plasticity) between cancer glioblastoma stem cells and tumor more differentiated cells and, by this way, influence the GBM recurrence after surgery." (PMID 30514244, 2018). "Analysis of Allen Brain - Ivy Glioblastoma Atlas data showed us that EMX2-mRNA levels are specifically reduced by ≥2-folds in GBM tumors with respect to surrounding tissue." (PMID 27191499, 2016). "Here we show that, in all GBM lines tested, Emx2 overexpression suppresses glioblastoma growth, both in vitro and in vivo." (PMID 27191499, 2016). "However, EMX2’s mechanism of action in glioblastoma remains unclear." (PMID 30514244, 2018). "To assess if Emx2 can antagonize glioblastoma multiforme, we overexpressed its coding sequence in 2 GBM lines (U87MG and T98G) as well as in GBM cell cultures originating from 5 different patients (GbmA, GbmB, GbmC, GbmD and GbmE), via lentiviral vectors and TetON technology." (PMID 27191499, 2016). "While the precise regulatory mechanisms governing EMX2 expression in ESCC remain unclear, epigenetic modifications such as promoter methylation and histone modifications may play a role, as suggested by studies in esophageal, glioblastoma, and ovarian cancers." (PMID 40564092, 2025).
colorectal cancer (4 papers, 2017 to 2023). A primary or metastatic malignant neoplasm that affects the colon or rectum. "Furthermore, EMX2 down-regulation in colorectal cancer tissue was associated with distant metastasis (M1) and impaired overall patient survival." (PMID 28830374, 2017). "EMX2 is frequently down-regulated in both primary colorectal cancer and colorectal cancer liver metastases." (PMID 28830374, 2017). "In search for a suitable in vitro model, imitating up- or down-regulation of EMX2, we screened various colorectal cancer cell lines for their EMX2 expression levels." (PMID 28830374, 2017). "In summary, our data encourage a significant role of EMX2 in the progression and metastasis of colorectal cancer." (PMID 28830374, 2017). "In this study, we analyzed the specific expression of EMX2 transcripts in colorectal cancer and corresponding healthy mucosa from 31 patients and investigated putative clinical correlations." (PMID 28830374, 2017). "Collectively, these in vitro data confirm the notion that EMX2 down-regulation in colorectal cancer cells affects their migratory potential, thus contributing to an increased rate of distant metastasis and unfavorable outcome." (PMID 28830374, 2017). "siRNA-mediated knockdown and adenoviral delivery-mediated overexpression of EMX2 were performed in order to investigate its effects on the migration of colorectal cancer cells in vitro." (PMID 28830374, 2017). "Given that EMX2 transcript levels were downregulated in primary colorectal cancer as well as colorectal liver metastases, we sought to determine protein levels of EMX2 by means of immunohistochemistry and Western blotting." (PMID 28830374, 2017). "Further, we provide evidence that EMX2 has predictive value as a prognostic factor in stage III colorectal cancer as well as a possible functional role in metastatic spread." (PMID 28830374, 2017). "EMX2 is frequently down-regulated in human colorectal cancer, and down-regulation of EMX2 is a prognostic marker for disease-free and overall survival." (PMID 28830374, 2017). "Expression levels of EMX2 in human colorectal cancer and adjacent mucosa were assessed by qRT-PCR technology, and results were correlated with clinical and survival data." (PMID 28830374, 2017). "Thus, the study at hand provides a first evidence for the role of EMX2 as a suppressor of metastasis in colorectal cancer." (PMID 28830374, 2017). "Thus, these previous observations support our present finding that down-regulation of EMX2 has protumorigenic effects in colorectal cancer." (PMID 28830374, 2017). "While recent studies provide evidence that EMX2 regulates tumorigenesis of various solid tumors, its role in colorectal cancer remains unknown." (PMID 28830374, 2017). "Moreover, we applied over- and underexpression of EMX2 in vitro in order to assess its functional significance in colorectal cancer spread." (PMID 28830374, 2017). "EMX2 might represent a promising molecular target for colorectal cancer therapy." (PMID 28830374, 2017). "Indeed, EMX2 expression levels were further down-regulated in colorectal cancer liver metastases compared to primary tumor tissue from patients suffering stage III colorectal cancer." (PMID 28830374, 2017). "EMX2 might thus represent a promising therapeutic target in colorectal cancer." (PMID 28830374, 2017). "Taken together, these results indicate that decreased EMX2 expression predicts metastatic progression and unfavorable outcome in stage III colorectal cancer." (PMID 28830374, 2017). "Down-regulated EMX2 is a strong predictor for shortened disease-free and overall survival in stage III colorectal cancer." (PMID 28830374, 2017). "Our study demonstrates that a low EMX2 expression level is an independent prognostic factor and correlates with dismal prognosis, decreased overall survival and the development of metastatic disease in stage III colorectal cancer patients." (PMID 28830374, 2017).
colorectal cancer (continued). "However, to our knowledge, no study has evaluated the role of EMX2 in colorectal cancer thus far." (PMID 28830374, 2017).